PFKFB3 (6-phosphofructo-2-kinase/fructose-2,6-biphosphatase 3)
Diseases named in the same sentence as PFKFB3 in open-access papers (continued):
Sharing a sentence is not in itself a finding about the gene and the disease.
tumor (continued). "Our results indicate that aminoquinoxaline derivatives have the potential to be developed as a “theranostic” probe for tumor diagnosis and treatment, but further comprehensive studies are needed to fully investigate the SAR of this scaffold with PFKFB3." (PMID 37035116, 2023). "Our study suggested that PFKFB3 is a potent regulatory factor for the TME and has the potential to be a valuable prognostic biomarker in human tumor therapy." (PMID 37253634, 2023). "The hot genes with the most positive signal events in the normal-specific group were RBPJ, PFKFB3, CAMK1D, ACACB, and WWOX, whereas the hot genes in the tumor-specific group were SLC35F3, PCDH7, NF1, and RAB27B." (PMID 36895481, 2023). "Our data showed that both ENO1, PFKFB3, NSDHL and SQLE have high expression levels in clinical HNSCC samples, and all of them presented higher expression in patient with recurrence tumor." (PMID 36841765, 2023). "Our study indicated that PFKFB3 is a potent regulatory factor for TME and has the potential to be a valuable prognostic biomarker in human tumor therapy." (PMID 37253634, 2023). "In particular, we identified a specific signature of glycolysis-related genes in BRAF-like tumours, which display the overexpression of SLC2A1, SLC2A3, HK3, PFKFB3, PKM, LDHA and SLC16A3 (alias Mct4, the membrane channel regulating lactate efflux)." (PMID 37198319, 2023). "Other important proteins which can be involved in glucose flow between glycolysis and the oxidative arm of PPP are tumor-specific isoenzymes of phosphofructokinase II, PFKFB3 (6-phosphofructo-2-kinase/fructose-2,6-biphosphatase 3) and PFKFB4." (PMID 37332080, 2023). "PFKFB3, together with HK2, play major roles in glycolysis that are occasionally overexpressed in aberrant tumor microenvironments (TMEs)." (PMID 38132178, 2023). "Its isoform PFKFB3 activates PFK1 allosterically, which promotes the synthesis of fructose 2,6‐diphosphate and the tumor glycolysis process." (PMID 36994237, 2023). "To confirm the tumor-promoting function of PFKFB3 in TC, we used two different siRNAs to knock down PFKFB3 in KTC-1 and found that PFKFB3 knockdown significantly increased the ADP/ATP ratio and reduced the phosphorylation level of ERK and AKT." (PMID 36990998, 2023). "A combination therapy with PFKFB3 inhibitor and VEGF inhibitor, bevacizumab, improved tumor vasculature, alleviated tumor hypoxia, normalized lactate production, and improved the efficacy and delivery of doxorubicin in glioblastoma." (PMID 36768924, 2023). "PFKFB3 is also a key effector protein to TGF-β, which has been proven to be an EMT inducer in tumor cells, aiding the metastasis stage of tumor development." (PMID 36551290, 2022). "Knockdown of PFKFB3 or blocking PFKFB3 with 3PO/PFK158 reduced lactate production, sensitized resistant cells to cisplatin treatment and inhibited CSC properties and tumor growth." (PMID 35155224, 2022). "PFKFB3 knockdown and PFK158 treatment in a H1048 SCLC cancer stem cell-enriched mouse xenograft model showed significant reduction in tumor growth and weight with reduced expression of cancer stem cell markers, ABCG2, and YAP/TAZ." (PMID 35804016, 2022). "Inhibition of AMPK in OR CRC cells induces tumor-suppressive autophagy through inactivation of Akt/mTOR pathway and decrease in the level of GLUT1, PFKFB3 and PFK1." (PMID 36359211, 2022). "In this study, we demonstrated that LINC00930 epigenetically upregulated PFKFB3 and activating glycolysis process and cell cycle progression at the G1/S phase transition, thus regulating NPC cell proliferation and tumor growth." (PMID 35209949, 2022). "Targeting PFKFB3 and PFKFB4 in tumor cells has been shown in a few in vitro studies to inhibit glycolysis, thereby slowing tumor development." (PMID 36276846, 2022). "A recent study indicated that PFKFB3 was also a key effector protein in TGF-β/Smad signaling pathway, which involved in EMT of tumor cells." (PMID 35094634, 2022).
tumor (continued). "Collectively, our findings establish a novel mechanism of lncRNA regulating tumor metabolism, of which LINC00930 regulates the key glycolytic gene PFKFB3 by epigenetic modification." (PMID 35209949, 2022). "Knowing that a tumor-promoting metabolic reprograming is found in several malignancies, including CRC, it is imperative that PFKFB3 inhibition should be studied further." (PMID 33671096, 2021). "The main focus is on the latest reports in this field of cancer research, and in particular the impact of PFKFB3 and PFKFB4 on tumor progression, metastasis, angiogenesis, and autophagy." (PMID 33671514, 2021). "PFKFB3 silencing has been observed to reduce the expression of Akt, pAkt, and ERCC1 with subsequent accumulation of DNA damage, tumor cell death, and reduced tumor growth." (PMID 34831136, 2021). "The use of PFKFB3 inhibitors has synergistic effects with chemotherapeutic and radiotherapeutic modalities via mitigation of TMR, promoting anti-tumor cytotoxicity, prolonging TVN, and modulating immune suppressive cells." (PMID 34831136, 2021). "In addition, PFKFB3 knockdown could also suppress the tumor growth in vivo." (PMID 34612136, 2021). "To date, the promising strategy to target tumor angiogenesis metabolically together with a sensitization of CRC to chemo- and/or radiotherapy by PFKFB3 (6-phosphofructo-2-kinase/fructose-2,6-biphosphatase-3) inhibition has never been tested." (PMID 33671096, 2021). "Among them, PFKFB3 and PFKFB4 protein expression is important in tumor cell proliferation and survival." (PMID 33803236, 2021). "The enzymes 6-phosphofructo-2-kinase/fructose-2,6-bisphosphatase-3 (PFK2/PFKFB-3) play a significant role in the regulation of glycolysis in HCC, as well as in tumor growth and metastasis." (PMID 32631382, 2020). "We here first reported a novel combined strategy by dual inhibition of VEGF and PFKFB3 to sustain TVN effect, thereby alleviating tumor hypoxia, reducing lactate production, and improving chemotherapy efficacy." (PMID 32641990, 2020). "The compression-induced upregulation of ENO2, HK2, and PFKFB3 genes was confirmed in the CAF cells exposed to 0.386 kPa, the compressive stress value of a native tumor microenvironment, using real-time PCR analysis." (PMID 31428701, 2019). "Inhibition of PFKFB3 induced downregulation of ERCC1 followed by accumulated DNA damage, resulting in G2/M arrest and tumor growth delay." (PMID 29559632, 2018). "In conclusion, this study showed that PFKFB3 expression promotes HCC growth through the PFKFB3/AKT/ERCC1 signaling pathway to enhance the ability of DNA repair and its pro-tumor effects during glycolysis." (PMID 29559632, 2018). "A recent in vitro study found that PFKFB3 is a key effector protein of transforming growth factor β1 (TGFβ1), which is an inducer of epithelial–mesenchymaltransition (EMT) in tumor cells, further suggesting a role of PFKFB3 in the cancer invasion process." (PMID 29263928, 2017). "It should also be pointed out that 3PO treatment at CT7, but not at CT19, was more effective at decreasing the expression of PFKFB3 and CLOCK in implanted neoplasms." (PMID 27079271, 2016). "We therefore simulated PFKFB3 blockade also in more extreme VEGF levels (10 × VEGF), corresponding with late-stage tumours." (PMID 27436424, 2016). "Accordingly, on-going efforts are directed at understanding the relative roles of PFKFB3 and PFKFB4, and at examining the anti-tumor effects of dual Pfkfb3 and Pfkfb4 genomic deletion as well as combined PFK-158 and 5MPN administration." (PMID 26221874, 2015). "Lactate dehydrogenase B (LDH-B) is upregulated in tumor endothelium, and VEGF signaling increases glycolytic flux by inducing GLUT1 and the glycolytic enzyme 6-phosphofructo-2-kinase/fructose-2,6-bisphosphatase-3 (PFKFB3)." (PMID 25063693, 2014).
tumor (continued). "We hypothesized that the combination of the PFKFB3 inhibitor 3PO with the autophagy inhibitor CQ might lead to a significant improvement in the anti-cancer effects of 3PO in vitro and that this combination might also increase efficacy of 3PO as an anti-tumor agent in vivo." (PMID 24451478, 2014). "The smaller tumor size and increased cleaved caspase-3 staining supports the idea that autophagy is serving as a protective mechanism following PFKFB3 inhibition and that the efficacy of PFKFB3 inhibitors as anti-cancer agents may be improved using autophagy inhibitors such as CQ." (PMID 24451478, 2014). "The inducible isoform of PFKFB3 (i-PFK2) has been reported to be overexpressed in several human cancer cell lines if compared to normal cells, and has been shown to be required for tumor cell growth in vitro and in vivo." (PMID 24280138, 2013). "The novel PFKFB3 inhibitors, N4A and YN1 reduced the Fru-2,6-BP levels and glycolytic flux, resulting in growth inhibition of tumor cells and massive cell death." (PMID 21957443, 2011). "Tumor-suppressive miRNAs converge on glycolysis by directly repressing rate-limiting nodes—HK2 (miR-125a/miR-885-5p), PFKFB3/GLUT1/c-Myc axis (miR-192-5p), and HIF-1α (miR-199a-5p/miR-3662), reducing glucose influx and lactate production and favoring mitochondrial oxidation." (PMID 41007803, 2025). "Further downstream of PFKFB3 and FBP1, glyceraldehyde 3-phosphate dehydrogenase (GAPDH) is elevated in TECs in human colorectal cancer (CRC) tissue compared to adjacent tissue ECs, contributing to the dysregulated tumor blood vessel phenotype." (PMID 39567756, 2025). "After MWA, tumor-promoting genes such as BCL3, Myh10, NR6A1, and PFKFB3 displayed downregulation." (PMID 38779358, 2024). "Last, as the goal of our study was to examine the role of the PFKFB3 enzyme in glycolytic regulation, we did not address the functions of other enzymes and pathways that play important roles in glucose metabolism and tumor growth." (PMID 39001392, 2024). "To control for unanticipated effects of TAM on tumor growth, we also examined tumor growth in Erbb2/Cre/Pfkfb3+/+ mice (WT for Pfkfb3) with and without TAM administration and observed similar growth in both groups." (PMID 39001392, 2024). "We examined tumor sections by immunohistochemistry for Ki67 expression and found a marked decrease in Ki67-positive cells in TAM-treated tumors relative to control tumors suggesting that genomic deletion of Pfkfb3 decreases cell cycle progression in vivo." (PMID 39001392, 2024). "Tumor vessel normalization, achieved through targeting glycolytic enzymes like PFKFB3 176, PKM2 177, TRPM7 178 and PDK 179 emerges as a promising anticancer strategy by improving vessel maturity and perfusion, thereby reducing tumor aggressiveness and enhancing chemotherapy effectiveness." (PMID 39479443, 2024). "Hence, PFKFB3 may be a tumor-associated antigen rather than a tumor-specific antigen." (PMID 37476196, 2023). "Our in vivo study indicated that PFKFB3 affected cell invasion but had no direct effect on tumor growth or metastasis." (PMID 37476196, 2023). "Furthermore, we observed that ENO1, PFKFB3, NSDHL and SQLE were highly expressed in recurrent HNSCC tumor compared with first diagnosed HNSCC patients surviving at least 5 years." (PMID 36841765, 2023). "Thus, additional studies are needed to explore the protein levels of phosphorylated PFKFB3 and PFKFB4 in tumor tissues of OSCC patients." (PMID 37919747, 2023). "While PFKFB3 has been proved as an oncogene relating to cell proliferation, survival, and invasion, it is important to understand its role in the angiogenesis of TME, including tumor cells and vascular endothelial cells (ECs)." (PMID 35784750, 2022).
tumor (continued). "Our results show that PFKFB3-mediated targeting by PFK158 or genetic manipulation resulted in inhibition of glycolysis and of tumor progression, resulting in diminished cancer “stemness” by decreasing both surface and intracellular stem cell marker expressions such as CD133, CD44, Aldh1, and Sox2." (PMID 35804016, 2022). "Targeting PFKFB3 to inhibit endothelial glycolysis promoted tumor vessel normalization, increased drug delivery and decreased metastasis." (PMID 36381236, 2022). "In contrast, the phospho-AMPK and Akt/mTOR signaling pathways were activated in OR CRC cells, reducing tumor-suppressive autophagy, which protects these cells by increasing the levels of enzymes involved in glycolysis, especially GLUT1, PFKFB3 and PFK1, thereby maintaining resistance to oxaliplatin." (PMID 36359211, 2022). "Anatomical appearance of flank-containing tumor shows that inhibition of PFKFB3 by PFK158 and genetic knockdown with shPFKFB3 regressed CSC tumor size noticeably with 0.353 ± 0.28 g and 0.135 ± 0.025 g of tumor respectively, when corresponded to that of untreated (1.80 ± 0.6 g)." (PMID 35804016, 2022). "Thus, for neoplastic cells, both activities of cancer-specific PFK-II isoenzymes (PFKFB3, PFKFB4), although opposing, can significantly stimulate tumor progression." (PMID 34445551, 2021). "Therefore, not only the regulation of expression of cancer-specific PFKFB3 and PFKFB4 isoforms but also the regulation/modulation of the activity of two opposing domains will be crucial for the tumor progression." (PMID 34445551, 2021). "Overexpression of both PFKFB3 and TIGAR has been observed in several tumours, where parallel increases of glycolysis and the PPP provide cells with enhanced ATP, Ribose-5-P, and TCA intermediates required for biosynthesis, together with NADPH to control ROS levels." (PMID 34299056, 2021). "Lack of a PTEN tumor suppressor function prevents cells from degrading PFKFB3 by the APC/C-Cdh1 mechanism." (PMID 34831136, 2021). "In tumor cells, antagomir treatment significantly reduced the miR-375 amount in both cell lines, which was in line with increased LDHB and reduced PFKFB3 mRNA expression, while LDHA remained unaltered." (PMID 34158867, 2021). "Tumor cells often express high levels of the glycolytic enzymes hexokinase 2 (HK2) and 6-phosphofructo-2-kinase/fructose-2,6-biphosphatase 3 (PFKFB3), or switch isoforms of metabolic enzymes such as PKM (Alves-Filho and Pålsson-McDermott, 2016; Lincet and Icard, 2015)." (PMID 34345916, 2021). "Tumor cells also secrete vascular endothelial growth factor (VEGF) into the TME, resulting in the upregulation of 6-phosphofructo-2-kinase/fructose-2, 6-biphosphatase 3(PFKFB3) in endothelial cells, which activates PFK-1 to promote the glycolytic phenotype as well as proliferation." (PMID 34926283, 2021). "Anti-PFKFB3 treatment increased vessel lumen size and the total perfusable area of the tumor without altering the overall vessel density." (PMID 34831136, 2021). "Apart from regulating the process of angiogenesis, manipulating PFKFB3 showed it has a non-canonical role in rebuilding and normalizing the tumor vasculature." (PMID 33777937, 2021). "A series of elegant experiments has unequivocally shown that glycolytic metabolism activates the YAP/TAZ signal in cells of different neoplasms (e.g., breast and liver) and YAP activation upregulates the expression and transcriptional activity of HK2 and PFKFB3." (PMID 33008042, 2020). "Accordingly, BrdU incorporation and cell accounting analysis in tumor cells indicated that hypoxia slightly suppressed the proportion of divided cells, which was aggravated by PFKFB3 or OGT depletion, but without an additional effect when both were depleted." (PMID 32060258, 2020).
tumor (continued). "For instance, blockade of 6-Phosphofructo-2-Kinase/Fructose-2, 6-Biphosphatase 3 (PFKFB3), a key regulator of glycolysis in ECs, normalizes tumor vessels with increased pericytes coverages and enhances EC barrier function through decreased VE-cadherin endocytosis." (PMID 33049983, 2020). "Consistently, many genes coding for key glycolytic enzymes such as GLUT1, HK2, PFKFB3, PFKP, and PKM2 were significantly upregulated in HCC192Low tumors compared to HCC192High tumors but showed negligible alteration in their non-tumor tissues." (PMID 33256802, 2020). "In tumour ECs, VEGF-A and PFKFB3 play a major role in enhancing EC metabolism since inhibition of Prostaglandin endoperoxide synthase 2, also known as cyclooxygenase-2 (COX-2) decreases the expression of VEGF-A and PFKFB3 and reduces the glycolysis rate to the level of normal ECs." (PMID 32911833, 2020). "Meanwhile, immunoprecipitation analysis of tumor tissues, with WT PFKFB3 but not PFKFB3 S172A, showed the PFKFB3-S172 phosphorylation and PFKFB3-G3BP2 interaction were enhanced by OGT depletion." (PMID 32060258, 2020). "Moreover, PFKFB3 is required for RAS-induced cellular transformation, underscoring the importance of PFKFB3-mediated glycolysis regulation during tumor development." (PMID 31569510, 2019). "The tumor suppressor PTEN promotes APC/C-Cdh1 activity and cells from mice that overexpress PTEN show APC/C-Cdh1-mediated degradation of PFKFB3 and glutaminase, resulting in a decrease of glycolysis and proliferation, and an increase in resistance to oncogenic transformation." (PMID 30234009, 2018). "Of note, blocking PFKFB3 does not reduce tumor growth in tumor mouse models and does not affect the number of tumor blood vessels, but rather induces vessel normalization." (PMID 28665313, 2017). "A more recent study showed however that endothelial haplodeficiency of PFKFB3 does not inhibit tumor growth but reduces metastasis and improves the delivery and response to chemotherapy, by normalizing tumor vessels." (PMID 28081641, 2017). "Unlike traditional antiangiogenic agents, PFKFB3 haplodeficiency or blockade does not reduce tumor vessel density or total vascular area." (PMID 28081641, 2017). "A hypoxic environment induces PFKFB3 upregulation in CSCs, tumor cells, and iPS cells, but not in normal fibroblasts." (PMID 28977989, 2017). "In this regard, the contribution from host cells to the overall outcomes of PFKFB3 inhibition on the implanted neoplasms cannot be ruled out." (PMID 27079271, 2016). "Furthermore, expression of PFKFB3, PFKFB4 and PDK1 was decreased by MTG16-expression; these genes are key regulators of glucose metabolism in tumor cells." (PMID 23840896, 2013). "Mechanistically, Mettl3 stabilizes Pfkfb3 mRNA through N6-methyladenosine (m6A) modification and subsequently induces lactate production to upregulate the PD-L1 expression via H3K18 lactylation, thereby promoting both tumor growth and CDDP-induced renal damage." (PMID 40765834, 2025). "Additionally, although PFKFB3 inhibitors have inhibition effects on tumour growth, they do not necessarily block PFKFB3 nuclear translocation and ameliorate radiotherapy resistance." (PMID 41292194, 2025). "Blocking of the glycolysis activator PFKFB3 in EC cells does not affect tumor growth." (PMID 39729352, 2024). "Recent studies have revealed that 6-phosphofructo-2-kinase/fructose-2,6-biphosphatase 3 (named PFKFB3), a bifunctional enzyme in glycolysis, is upregulated in a variety of malignant solid tumors and has been regarded as a potential biomarker for the diagnosis and treatment of tumor patients." (PMID 37035116, 2023). "Our results indicate that PFKFB3 (but not PFKFB4) might be involved in tumor growth through regulating G2/M cell cycle progression in OSCC." (PMID 37919747, 2023). "However, CpG islands of genes encoding glucose transporters and glycolysis-related enzymes do not display—except PFKFB3 — significant methylation changes between tumour subtypes." (PMID 37198319, 2023).